WDR35 (WD repeat domain 35)
Description:
As a component of the IFT complex A (IFT-A), a complex required for retrograde ciliary transport and entry into cilia of G protein-coupled receptors (GPCRs), it is involved in ciliogenesis and ciliary protein trafficking. May promote CASP3 activation and TNF-stimulated apoptosis.
Synonyms: IFT121; KIAA1336; MGC33196; IFTA1; FAP118; CFAP118; CED2; SRTD7
Tractability: PROTAC: ubiquitination databases record sites on it; its protein half-life has been measured.
Gene: Protein-coding gene on chromosome 2 (19,910,263 to 19,990,141, reverse strand). Ensembl gene ENSG00000118965.
Subcellular location: Cytoplasm, cytoskeleton, microtubule organizing center, centrosome; Cytoplasm, cytoskeleton, cilium axoneme; Cytoplasm, cytoskeleton, cilium basal body
Pathways (Reactome):
Organelle biogenesis and maintenance: Intraflagellar transport
Signal Transduction: Hedgehog 'off' state
Gene Ontology:
Molecular function: protein binding; protein carrier chaperone
Biological process: cilium assembly; intraciliary anterograde transport; intraciliary retrograde transport; intraciliary transport; protein localization to cilium; protein localization to non-motile cilium
Cellular component: intraciliary transport particle A; axoneme; centrosome; ciliary basal body; ciliary tip; cilium
Genetic constraint (gnomAD): Loss-of-function variants: 101 observed, 153.51 expected, observed/expected ratio (o/e) 0.66, 90% interval 0.56 to 0.78. The upper end of that interval is the gene's LOEUF score, 0.78, which puts it in group 3 of 6, group 1 being the genes least tolerant of losing a copy. Missense variants: 1,190 observed, 1,395.1 expected, observed/expected ratio (o/e) 0.85, 90% interval 0.81 to 0.89. Synonymous variants: 425 observed, 477.55 expected, observed/expected ratio (o/e) 0.89, 90% interval 0.82 to 0.96.
Gene-disease validity (ClinGen):
ClinGen rates the evidence that WDR35 causes each of these diseases.
cranioectodermal dysplasia 2 (autosomal recessive): Definitive.
short-rib thoracic dysplasia 7 with or without polydactyly (autosomal recessive): Definitive.
Homologues: Orthologues: chimpanzee WDR35 (99% identical), macaque WDR35 (99% identical), dog WDR35 (94% identical), rabbit WDR35 (93% identical), pig WDR35 (93% identical), rat Wdr35 (93% identical), mouse Wdr35 (92% identical), guinea pig WDR35 (88% identical), tropical clawed frog wdr35 (83% identical), zebrafish wdr35 (79% identical), Drosophila melanogaster Oseg4 (48% identical), Caenorhabditis elegans ifta-1 (32% identical). Paralogues in human: TULP4 (21% identical), TUB (7% identical), TULP2 (6% identical), TULP1 (6% identical), TULP3 (5% identical).
Diseases named in the same sentence as WDR35 in open-access papers:
WDR35 is named in the same sentence as 32 diseases in open-access papers, as found by Europe PMC text mining. Sharing a sentence is not in itself a finding about the gene and the disease. The quoted sentences say what the papers report.
cranioectodermal dysplasia (22 papers, 2012 to 2024). Cranioectodermal dysplasia (CED) is a rare developmental disorder characterized by congenital skeletal and ectodermal defects associated with dysmorphic features, nephronophthisis, hepatic fibrosis and ocular anomalies (mainly retinitis pigmentosa). "WDR35 variants are known to cause a rare autosomal recessive disorder-Cranioectodermal dysplasia (CED)." (PMID 37596520, 2023). "Mutation in the related gene WDR35 has been implicated in cranioectodermal dysplasia, also known as Sensenbrenner syndrome, an autosomal recessive condition characterised by craniofacial and skeletal abnormalities." (PMID 32216834, 2020). "Mutations in IFT121/WDR35 result in cranioectodermal dysplasia, short rib polydactyly syndrome, Ellis–van Creveld syndrome and respiratory dysfunction." (PMID 29514868, 2018). "For instance, WDR35 heterozygous mutations, a gene involved in retrograde ciliary transport, ciliogenesis, and ciliary protein trafficking, caused motile cilia dysfunction in Sensenbrenner syndrome." (PMID 36140829, 2022). "Some examples of new disease-associated genes that have been discovered using NGS technologies are DHODH, the causative gene of the Miller syndrome, WDR35, the gene that is responsible for Sensenbrenner syndrome, and SETBP1, which is responsible for the Schinzel–Giedion syndrome (SGS)." (PMID 34827709, 2021). "To date, more than 60 patients have been reported in literature and mutations in six genes have been associated with Sensenbrenner syndrome: IFT122, WDR35, IFT140, IFT43, IFT52 and WDR19." (PMID 32007091, 2020). "Recent studies have demonstrated that the WDR35 gene is involved in several human diseases such as type 2 diabetes, acute lymphoblastic leukemia, coronary artery disease, and Sensenbrenner syndrome." (PMID 24859235, 2014). "Recent studies demonstrated that the WDR35 gene is involved in several human diseases such as type 2 diabetes, acute lymphoblastic leukemia, coronary artery disease, and Sensenbrenner syndrome." (PMID 24466034, 2014). "More recently, clinical studies have identified relationships between the WDR35 gene and coronary artery disease and Sensenbrenner syndrome." (PMID 23227925, 2012). "Notably, some WD40 repeat proteins were reported to be associated with rare disorders, for example, WDR45 with psychomotor development delay, WDR35 with cranioectodermal dysplasia, and WDR56 with short‐rib thoracic dysplasia, etc.." (PMID 35962600, 2022). "WDR35/IFT121 encoding an intraflagellar transport protein is an example of another gene whose mutations were previously associated only with ciliopathies caused by the dysfunction of the primary cilia, such as cranioectodermal dysplasia." (PMID 31835861, 2019). "For example, Sensenbrenner syndrome (also known as cranioectodermal dysplasia), a ciliopathy characterized by sagittal craniosynostosis with accompanying facial, skeletal, and ectodermal anomalies, is caused by mutations in the IFT-A genes IFT43, WDR35, IFT122, WDR19, and IFT140." (PMID 28724397, 2017). "Additionally, as controls for the analysis below, we examined primary fibroblasts derived from two Sensenbrenner Syndrome patients, which carry distinct defects in genes encoding primary cilia intraflagellar transport (IFT) proteins, namely WDR35 (also called IFT121) or IFT43." (PMID 23516378, 2013). "Three patients had biallelic mutations in WDR35; two patients (siblings) had cranioectodermal dysplasia (CED) and one patient had a ciliopathy phenotype that did not constitute a recognizable syndrome." (PMID 29974258, 2018). "WDR35 and SOX9 were related to known craniofacial malformations, i.e., cranioectodermal dysplasia 2 and campomelic dysplasia, respectively." (PMID 29921221, 2018).
ciliopathy (11 papers, 2014 to 2025). A genetic disorder of the cellular cilia or the cilia anchoring structures, the basal bodies, or of ciliary function. "To date, 22 missense variants have been described in the WDR35 gene in patients with a ciliopathy-related phenotype, of which 13 changes were found in CED-affected individuals (HGMD, 11th October 2023)." (PMID 38161384, 2023). "Of note, a dual molecular diagnosis is observed in the patient 13DG0792, who is homozygous for the founder variant PTRHD1 and a ciliopathy phenotype (Caroli disease) caused by the variant WDR35 [NM_001006657.1:c.206G>A; p.(Gly69Asp)]." (PMID 33456446, 2020). "In C. elegans, the IFTA-1 protein was shown to be a component of the IFT complex, a strong indication that mutation of the human ortholog WDR35 would likely result in typical ciliopathy phenotypes." (PMID 25780610, 2014).
neuroblastoma (4 papers, 2012 to 2014). Neuroblastoma (NB) is the most common solid, extracranial childhood tumor. "Recently, we demonstrated that bupivacaine induces ROS generation and p38 MAPK activation, resulting in an increase in WDR35 expression in mouse neuroblastoma Neuro2a cells." (PMID 24859235, 2014). "Very recently, we found that the local anesthetic bupivacaine increases intracellular ROS levels and activates p38 MAPK, resulting in apoptosis via an increase in WDR35 expression in mouse neuroblastoma Neuro2a cells (under revision)." (PMID 23289926, 2013). "Very recently, we have found that bupivacaine, a local anesthetic, increases intracellular ROS levels and activates p38 MAPK in mouse neuroblastoma Neuro2a cells, resulting in apoptosis via an increase in the expression of WDR35 (under revision)." (PMID 23289926, 2013). "Recently, we reported that bupivacaine induces reactive oxygen species (ROS) generation and p38 mitogen-activated protein kinase (MAPK) activation, resulting in an increase in the expression of WD repeat-containing protein 35 (WDR35) in mouse neuroblastoma Neuro2a cells." (PMID 24466034, 2014). "The present study was undertaken to investigate whether bupivacaine induces apoptosis in the mouse neuroblastoma Neuro2a cell line and to examine the potential involvement of WDR35, ROS, and p38 MAPK in bupivacaine-induced Neuro2a cell neurotoxicity." (PMID 23227925, 2012). "The present study was undertaken to test whether bupivacaine induces apoptosis in mouse neuroblastoma Neuro2a cells and to determine whether ROS, p38 MAPK, and WDR35 are involved." (PMID 23227925, 2012).
Jeune syndrome (2 papers, 2013 to 2022). Jeune syndrome, also called asphyxiating thoracic dystrophy, is a short-rib dysplasia characterized by a narrow thorax, short limbs and radiological skeletal abnormalities including "trident" aspect of the acetabula and metaphyseal changes. "Similarly, Sensenbrenner and Jeune syndromes appear to be milder presentations of the embryonically lethal short rib polydactyly syndrome as IFT80, WDR35 and DYNC2H1 are mutated in both milder and more severe phenotypes." (PMID 22829176, 2013).
polydactyly (2 papers, 2022 to 2024). A disease characterized by the presence of polydactyly, including syndromic and non-syndromic forms. "In this article, we report a novel deletion compound combined with a causative variant in WDR35 gene leading to short-rib thoracic dysplasia 7 (SRTD7) with or without polydactyly using WES." (PMID 39877340, 2024).
cyst (1 paper, 2023). A sac-like closed membranous structure that may be empty or contain fluid or amorphous material. "We demonstrate here that loss of the primary cilium on postnatal biliary epithelial cells (via the deletion of the cilia gene Wdr35) drives ongoing, pathological remodelling of the biliary tree, resulting in progressive cyst formation and growth." (PMID 37703354, 2023). "SMAD3 inhibition did not reduce the number of panCK-positive cysts in the Wdr35-/- liver; however, it reduced cyst size." (PMID 37703354, 2023).
dysplasia (1 paper, 2018). A usually neoplastic transformation of the cell, associated with altered architectural tissue patterns. "The WDR35 gene is related to cranioectodermal dysplasia 2 (CED2 [MIM 613610]), which manifests as forehead bossing, dolichocephaly, and metaphyseal dysplasis." (PMID 29921221, 2018).
liver cyst (1 paper, 2023). "Last, Wdr35-loss is simply a model of liver cyst formation and within patients there have been a suite of causative mutations identified." (PMID 37703354, 2023).
genetic disease (2 papers, 2023 to 2025). "This study expands our understanding of genotype-phenotype association in patients with WDR35 variants and provides genetic counseling for prevention and intervention in this genetic disorder." (PMID 37596520, 2023).
brain disorder (1 paper, 2013). A disease affecting the brain or part of the brain. "Therefore, we examined whether ROS might play a role in the DA-induced increase in WDR35 protein expression in the rat hippocampus by using the radical scavenger edaravone (10 mg/kg, i.p.)that has been shown to exert neuroprotective effects in animal models of several brain disorders." (PMID 23289926, 2013).
renal disease (1 paper, 2023). "Defects to the IFT-A complex of proteins (e.g., WDR35, IFT122, IFT43, IFT172, IFT140 and WDR19), can present with renal disease phenotypes such as chronic renal failure, NPHP, and renal cysts and, in some cases, isolated NPHP or NPHP-like nephropathy." (PMID 38292052, 2023).
WDR35 also shares sentences with these, for which no sentence is quoted: coronary artery disease (3 papers); acute lymphoblastic leukemia (2); short rib-polydactyly syndrome (2); type 2 diabetes (2); autosomal recessive deafness (1); breast carcinoma (1); campomelic dysplasia (1); Caroli disease (1); cleft palate (1); fibrosarcoma (1); infection (1); Joubert syndrome (1); Leber congenital amaurosis (1); Miller syndrome (1); multiple epiphyseal dysplasia (1); Neonatal respiratory distress (1); neurological disease (1); orofaciodigital syndrome (1); respiratory infections (1); situs inversus (1); tumor (1).